ZNF624 (zinc finger protein 624)
Description:
May be involved in transcriptional regulation.
Synonyms: KIAA1349
Tractability: PROTAC: ubiquitination databases record sites on it.
Gene: Protein-coding gene on chromosome 17 (16,620,734 to 16,653,856, reverse strand). Ensembl gene ENSG00000197566.
Subcellular location: Nucleus
Subcellular location (Human Protein Atlas): Vesicles
Pathways (Reactome):
Gene expression (Transcription): Generic Transcription Pathway
Gene Ontology:
Molecular function: protein binding; DNA-binding transcription factor activity, RNA polymerase II-specific; RNA polymerase II cis-regulatory region sequence-specific DNA binding
Biological process: regulation of transcription by RNA polymerase II; regulation of DNA-templated transcription
Cellular component: nucleus
Genetic constraint (gnomAD): Loss-of-function variants: 41 observed, 74.6 expected, observed/expected ratio (o/e) 0.55, 90% interval 0.43 to 0.71. The upper end of that interval is the gene's LOEUF score, 0.71, which puts it in group 2 of 6, group 1 being the genes least tolerant of losing a copy. Missense variants: 810 observed, 1,073 expected, observed/expected ratio (o/e) 0.75, 90% interval 0.71 to 0.8. Synonymous variants: 329 observed, 358.37 expected, observed/expected ratio (o/e) 0.92, 90% interval 0.84 to 1.01.
Homologues: Orthologues: chimpanzee ZNF624 (99% identical), dog ZNF624 (72% identical), rabbit ZNF624 (70% identical), pig ZNF624 (69% identical). Paralogues in human: ZNF254 (30% identical), ZNF841 (30% identical), ZNF28 (30% identical), ZNF726 (30% identical), ZNF229 (29% identical), ZNF606 (29% identical), ZNF41 (29% identical), ZNF568 (29% identical), ZNF724 (29% identical), ZNF836 (29% identical), ZNF33B (29% identical), ZNF546 (29% identical), and 164 more.
Diseases named in the same sentence as ZNF624 in open-access papers:
ZNF624 is named in the same sentence as 3 diseases in open-access papers, as found by Europe PMC text mining. Sharing a sentence is not in itself a finding about the gene and the disease. The quoted sentences say what the papers report.
depression (1 paper, 2021). "Additionally, four genes HELZ2, PTPRN2, GATA2, and ZNF624 were differentially expressed between depression cases and health controls." (PMID 34341332, 2021).
diabetes (1 paper, 2021). "Concerning the potential role of LPIN1 rs13412852, KLF6 rs3750861, SOD2 rs4880, TM6SF2 rs58542926, and ZNF624 rs12603226 SNPs in glycemic control of the patients with diabetes, data are also limited." (PMID 34746177, 2021).
cancer (1 paper, 2022). A tumor composed of atypical neoplastic, often pleomorphic cells that invade other tissues. "The role of the SLC9B1 and ZNF624 proteins on cancer is completely unknown, so the downregulation of their mutant protein isoforms and the prediction of their benign impact do not allow conclusions to be drawn." (PMID 35454907, 2022).